LINC00710 (long independently transcribed non-coding RNA 710)
Gene: Long non-coding RNA gene on chromosome 10 (10,917,866 to 10,952,234, reverse strand). Ensembl gene ENSG00000229240.
Diseases named in the same sentence as LINC00710 in open-access papers:
LINC00710 is named in the same sentence as 1 disease in open-access papers, as found by Europe PMC text mining. Sharing a sentence is not in itself a finding about the gene and the disease.
LINC00710 shares sentences with these, for which no sentence is quoted: male infertility (1 paper).